UBR1 (ubiquitin protein ligase E3 component n-recognin 1)
Description:
E3 ubiquitin-protein ligase which is a component of the N-end rule pathway. Recognizes and binds proteins bearing specific N-terminal residues that are destabilizing according to the N-end rule, leading to their ubiquitination and subsequent degradation. Recognizes both type-1 and type-2 N-degrons, containing positively charged amino acids (Arg, Lys and His) and bulky and hydrophobic amino acids, respectively. Does not ubiquitinate proteins that are acetylated at the N-terminus. In contrast, it strongly binds methylated N-degrons. Binds leucine and is a negative regulator of the leucine-mTOR signaling pathway, thereby controlling cell growth.
Synonyms: JBS
Tractability: PROTAC: ubiquitination databases record sites on it; its protein half-life has been measured.
Target class: Enzyme; Transferase
Gene: Protein-coding gene on chromosome 15 (42,942,897 to 43,106,113, reverse strand). Ensembl gene ENSG00000159459.
Subcellular location: Cytoplasm, cytosol
Subcellular location (Human Protein Atlas): Vesicles; Cytosol; Nucleoplasm
Pathways (Reactome):
Immune System: Antigen processing: Ubiquitination & Proteasome degradation
Gene Ontology:
Molecular function: L-leucine binding; protein binding; ubiquitin protein ligase activity; ubiquitin-protein transferase activity; zinc ion binding
Biological process: cellular response to L-leucine; negative regulation of TOR signaling; proteasome-mediated ubiquitin-dependent protein catabolic process; ubiquitin-dependent protein catabolic process via the N-end rule pathway; protein ubiquitination; protein catabolic process
Cellular component: cytosol; cytoplasm; ubiquitin ligase complex; proteasome complex
Genetic constraint (gnomAD): Loss-of-function variants: 80 observed, 204.86 expected, observed/expected ratio (o/e) 0.39, 90% interval 0.32 to 0.47. The upper end of that interval is the gene's LOEUF score, 0.47, which puts it in group 2 of 6, group 1 being the genes least tolerant of losing a copy. Missense variants: 1,603 observed, 2,009.1 expected, observed/expected ratio (o/e) 0.8, 90% interval 0.76 to 0.83. Synonymous variants: 620 observed, 666.33 expected, observed/expected ratio (o/e) 0.93, 90% interval 0.87 to 0.99.
Gene-disease validity (ClinGen):
ClinGen rates the evidence that UBR1 causes each of these diseases.
Johanson-Blizzard syndrome (autosomal recessive): Definitive. A multiple congenital anomaly characterized by exocrine pancreatic insufficiency, hypoplasia/aplasia of the nasal alae, hypodontia, sensorineural hearing loss, growth retardation, anal and urogenital malformations, and variable intellectual disability.
Homologues: Orthologues: macaque UBR1 (98% identical), dog UBR1 (96% identical), pig UBR1 (94% identical), rabbit UBR1 (94% identical), chimpanzee UBR1 (93% identical), mouse Ubr1 (93% identical), guinea pig UBR1 (93% identical), rat Ubr1 (92% identical), tropical clawed frog ubr1 (63% identical), zebrafish UBR1 (34% identical), Drosophila melanogaster Ubr1 (32% identical), Caenorhabditis elegans ubr-1 (28% identical), and 1 more. Paralogues in human: UBR2 (47% identical), UBR3 (21% identical).